C11orf97 (chromosome 11 open reading frame 97)
Synonyms: LINC01171
Gene: Protein-coding gene on chromosome 11 (94,512,461 to 94,532,125, forward strand). Ensembl gene ENSG00000257057.
Subcellular location: Cytoplasm, cytoskeleton, cilium basal body
Gene Ontology:
Cellular component: ciliary basal body; ciliary base
Genetic constraint (gnomAD): Loss-of-function variants: 5 observed, 5.86 expected, observed/expected ratio (o/e) 0.85, 90% interval 0.44 to 1.68. That is too few expected variants to judge how well the gene tolerates losing a copy. Missense variants: 104 observed, 81.23 expected, observed/expected ratio (o/e) 1.28, 90% interval 1.09 to 1.51. Synonymous variants: 43 observed, 33.5 expected, observed/expected ratio (o/e) 1.28, 90% interval 1 to 1.65.
Homologues: Orthologues: chimpanzee C11H11orf97 (95% identical), macaque C14H11orf97 (93% identical), pig C11orf97 (76% identical), guinea pig C11orf97 (75% identical), rabbit C11orf97 (72% identical), mouse 1700012B09Rik (71% identical), rat C8h11orf97 (71% identical).